FCN3 (ficolin 3)
Diseases named in the same sentence as FCN3 in open-access papers (continued):
Sharing a sentence is not in itself a finding about the gene and the disease.
lymphoma (2 papers, 2019 to 2020). A malignant (clonal) proliferation of B- lymphocytes or T- lymphocytes which involves the lymph nodes, bone marrow and/or extranodal sites. "Heterozygosity for +1637delC mutation of the FCN3 gene was more common among patients diagnosed with lymphomas who experienced hospital infections." (PMID 32047495, 2019). "The ROC analysis showed high potential of both ficolin-2 and ficolin-3 to differentiate between AML patients and controls as well as patients suffering from multiple myeloma or lymphomas." (PMID 32601370, 2020). "Both papers documented possible associations of factors specific for the lectin pathway of complement (especially on genetic background) with multiple myeloma or lymphoma (MBL, ficolin-1, ficolin-2) or hospital infections (MASP-2, ficolin-3)." (PMID 32047495, 2019).
nephritis (2 papers, 2016 to 2025). Inflammation of renal tissue. "This is in accordance with our results showing significantly higher anti-ficolin-3 titers in patients with active nephritis compared to those in patients with active disease but without renal involvement." (PMID 27631981, 2016). "Furthermore, Ficolin-3 (FCN3) is an important member of the fibrinogen family and an activator of the complement lectin pathway that, by causing pro-inflammatory effects, contributes to the onset/progression of inflammatory diseases, including nephritis." (PMID 40427671, 2025).
ovarian tumor (2 papers, 2013 to 2018). "We report for the first time the expression of the FCN2 and FCN3 genes in the ovary, their polymorphisms, and their serum concentrations in patients with ovarian tumours (both malignant and benign) as well as women operated on for reasons unconnected with ovarian tumours." (PMID 23744477, 2013).
primary immunodeficiencies (2 papers, 2022 to 2024). "Interestingly, of the newly identified associations, six include proteins encoded by MMDGs, 2 of which are known to cause primary immunodeficiencies, i.e., Ficolin-3 and FAS." (PMID 35264221, 2022). "Finally, we identified new genetic associations with plasma protein levels of five monogenic Mendelian disease genes including two primary immunodeficiency genes (Ficolin-3 and FAS)." (PMID 35264221, 2022).
proliferative diabetic retinopathy (2 papers, 2022 to 2024). Advanced retinopathy due to diabetes mellitus characterized by the formation of new vessels in the retina. "Furthermore, increased levels of ficolin-3 were observed in the vitreous humor and serum of patients with proliferative diabetic retinopathy." (PMID 38375199, 2024). "Interestingly, FCN3 was reported to be elevated in the vitreous of eyes with proliferative diabetic retinopathy along with increased VEGF suggesting a collaboration between FCN3 and VEGF to stimulate inflammation and angiogenesis." (PMID 35784369, 2022).
viral infections (2 papers, 2018 to 2020). "Still, high expression of Ficolin-3 found in both viral infections could be related to the inflammatory status seen in co-infected patients, contributing to the chronic process of these conditions." (PMID 30349535, 2018).
advanced heart failure (1 paper, 2013). Patients with advanced heart failure have severe limitations, experiences symptoms even while at rest and are mostly bedbound patients. "In this study we provide evidence, for the first time, that ficolin-3 the main activator of the lectin complement pathway may be associated with advanced heart failure." (PMID 23596511, 2013).
bladder cancer (1 paper, 2023). "Urine IL-8, Ficolin-3, Apolipoprotein L1, Properdin, and Proteinase 3 also need to be validated both independently and as a multi-marker panel in future cross-sectional and longitudinal cohorts to confirm if they are good indicators for bladder cancer disease progression." (PMID 37016361, 2023).
brain injury (1 paper, 2015). Acute and chronic (see also brain INJURIES, CHRONIC) injuries to the brain, including the cerebral hemispheres, CEREBELLUM, and brain STEM. "This prospective observatory study was designed to investigate the relationships between serum ficolin-3 levels and injury severity and clinical outcomes after severe traumatic brain injury." (PMID 26627059, 2015).
chronic heart failure (1 paper, 2013). "We hypothesized that the main initiator molecules of the lectin complement pathway mannose-binding lectin (MBL), ficolin-2 and ficolin-3 were related to disease severity and outcome in chronic heart failure." (PMID 23596511, 2013).
chronic renal failure (1 paper, 2016). "Moreover, the possibility that renal dysfunction might lead to higher level of antibody has been eliminated since anti-ficolin-3 antibodies were found negative in dialyzed patients with chronic renal failure." (PMID 27631981, 2016).
Cirrhosis (1 paper, 2020). A chronic disorder of the liver in which liver tissue becomes scarred and is partially replaced by regenerative nodules and fibrotic tissue resulting in loss of liver function. "We measured four different PRMs (mannose-binding lectin [MBL], ficolin-1, ficolin-2 and ficolin-3) using stored sera, and retrospectively analyzed the associations between PRMs and laboratory findings, histological findings, and the development of cirrhosis-related conditions." (PMID 32915797, 2020).
complement deficiencies (1 paper, 2023). "Among them, 3 have factor H deficiency (27.3% of all complement deficiencies), 3 have C1 inhibitor deficiency (27.3%), and 2 have ficolin 3 deficiency (18.2%)." (PMID 37559153, 2023). "The most frequent main genetic causes of complement deficiencies in children infected with SARS-CoV-2 were CFH (n = 3), SERPING1 (n = 3), and FCN3 (n = 2)." (PMID 37559153, 2023).
glaucoma (1 paper, 2020). Increased pressure in the eyeball due to obstruction of the outflow of aqueous humor. "Moreover, the five-protein panel consisting of complement C4a, complement factor H, ficolin-3, apolipoprotein A4, and transthyretin predicted the transition to glaucoma in 78% of cases, and to the advanced disease in 89%." (PMID 32585848, 2020). "As a proof of concept, the use of a five-protein panel, consisting of C4a, CFH, FCN3, APOA4, and TTR predicts the transition to glaucoma disease in 78% of cases." (PMID 32585848, 2020). "Moreover, the five-protein panel, consisting of C4a, CFH, FCN3, APOA4, and TTR, predicted the transition to glaucoma in 78% of cases and correctly classified 89% of cases with advanced glaucoma in this animal model." (PMID 32585848, 2020).
herpes zoster (1 paper, 2024). A common dermal and neurologic disorder caused by reactivation of the varicella-zoster virus that has remained dormant within dorsal root ganglia, often for decades, after the patient's initial exposure to the virus in the form of varicella (chickenpox). "These include elevated levels of cathepsin D and IL-18, which are associated with reduced risk of herpes zoster, as well as increased risk of postherpetic neuralgia with elevated levels of Ficolin-3 and IL-2 receptor α." (PMID 39253091, 2024).
idiopathic pulmonary fibrosis (1 paper, 2020). Idiopathic pulmonary fibrosis (IPF) is a nonneoplastic pulmonary disease that is characterized by the formation of scar tissue within the lungs in the absence of any known cause. "This study investigated the role of mannose-binding lectin (MBL), ficolin-2 and ficolin-3 in ILD patients with a focus on idiopathic pulmonary fibrosis (IPF) and sarcoidosis." (PMID 33101280, 2020).
interstitial lung disease (1 paper, 2019). A diverse group of lung diseases that affect the lung parenchyma. "Given that FCN-3 is also produced in the lungs, sufficient pulmonary FCN-3 levels may prevent extensive local inflammation as a consequence of apoptosis, and hence, lower levels may theoretically predispose SSc patients to interstitial lung disease." (PMID 30885245, 2019).
ischaemic cardiomyopathy (1 paper, 2023). "Our findings indicated that SERPINA3 and FCN3 might play a protective role in the pathological process of ischaemic cardiomyopathy by regulating immune cell infiltration." (PMID 36863704, 2023).
leiomyoma (1 paper, 2022). A well-circumscribed benign smooth muscle neoplasm characterized by the presence of spindle cells with cigar-shaped nuclei, interlacing fascicles, and a whorled pattern. "In a recent study, the potential of FCN3 in the therapeutic intervention of human leiomyoma was demonstrated." (PMID 35205837, 2022).
lentivirus infection (1 paper, 2024). Virus diseases caused by the Lentivirus genus. "To investigate this hypothesis, we first established stable cell lines overexpressing FCN3 through lentivirus infection and subsequently subjected them to erastin, a widely used inducer of ferroptosis." (PMID 38698462, 2024).
leukemia (1 paper, 2013). A malignant (clonal) hematologic disorder, involving hematopoietic stem cells and characterized by the presence of primitive or atypical myeloid or lymphoid cells in the bone marrow and the blood. "In addition, KNG1 and FCN3 potentially served as distinctive biomarkers for leukemia aggressiveness, whereas GELS played a restraining role as a suppressor protein in HR-ALL cases." (PMID 23849470, 2013).
myocardial infarction (1 paper, 2024). Gross necrosis of the myocardium, as a result of interruption of the blood supply to the area, as in coronary thrombosis. "Proteins involved in the complement and coagulation cascades, like MASP2, CRP, FCN3, and MBL2, were elevated, underlining the known importance of innate immunity and inflammation early in myocardial infarction." (PMID 39513871, 2024).
obstructive lung disease (1 paper, 2010). "We have recently described a patient suffering from recurrent infections and obstructive lung disease that was homozygous for the FCN3 + 1637delC mutation, resulting in complete deficiency of Ficolin-3." (PMID 21085669, 2010).
prostate carcinoma (1 paper, 2013). A carcinoma that arises from epithelial cells of the prostate gland. "Moreover, recent studies suggested the potential role of FCN3 in ovarian and prostate cancers." (PMID 23849470, 2013).
sarcoidosis (1 paper, 2020). Sarcoidosis is a multisystemic disorder of unknown cause characterized by the formation of immune granulomas in involved organs. "There was a weak positive correlation of BALF ficolin-3 with serum neopterin, a marker of sarcoidosis activity." (PMID 33101280, 2020). "Regarding ficolin-3, low plasma levels were related to the development of SSc-ILD and sarcoidosis, respectively, indicating that an impaired clearance of apoptotic cells due to decreased ficolin-3 levels might play an important role." (PMID 33101280, 2020). "Interestingly, a recent case-control study found a link between low ficolin-3 plasma levels and sarcoidosis." (PMID 33101280, 2020). "Our data suggests an involvement of pattern recognition receptors of the lectin complement pathway in sarcoidosis at the local level with significantly elevated lectin (MBL, ficolin-2, and ficolin-3) as well as complement split products (C4d and C5a) concentrations in the lungs of these patients." (PMID 33101280, 2020). "In line, ficolin-3 BALF (but not serum levels) correlated with neopterin, an activity marker of sarcoidosis." (PMID 33101280, 2020).
schizophrenia (1 paper, 2022). A major psychotic disorder characterized by abnormalities in the perception or expression of reality. "FCN3 can complex with mannose-associated serine proteases to activate the complement pathway, being ficolins’ activation already reported as a potential biomarker of the severity of schizophrenia." (PMID 35563307, 2022). "A meta-analysis between schizophrenia patients and healthy controls was performed, with the results suggesting four apolipoproteins, APOA1, APOA2, APOC1 and APOC3 (downregulated), and ficolin-3 (upregulated) as potential biomarkers of the disorder." (PMID 35563307, 2022).
systemic inflammatory response syndrome (1 paper, 2025). SIRS is a serious condition related to systemic inflammation, organ dysfunction, and organ failure. "In said study, individuals with serum FCN3 levels lower than 10.1 μg/mL had a high probability of experiencing systemic inflammatory response syndrome (SIRS) and multi-organ dysfunction (MODS)." (PMID 40332490, 2025).
cancer (25 papers, 2013 to 2026). A tumor composed of atypical neoplastic, often pleomorphic cells that invade other tissues. "Reports on the association between FCN3 with cancer are limited to its potential utility as a marker." (PMID 33859174, 2021). "In conclusion, the characteristic high systemic/low local ratio of ficolin-2 and ficolin-3 in ovarian and possibly other carcinomas warrants further investigation to explain these associations." (PMID 23744477, 2013). "Of these components, MBL2 and FCN3 are some of the mannose-binding lectin pathways’ complement initiators that bind to antigens on the cell membrane of cancer cells or cells, initiating the activation of the complement cascade." (PMID 39796711, 2024). "Previously, a lower expression of FCN3 has been found and proved either in tissue or serum from numerous cancer patients such as ovarian cancer, multiple myeloma, lymphoma, acute myeloid leukemia, head and neck cancer, and lung cancer 8,10-15." (PMID 37484802, 2023). "As mentioned, previous studies have shown longer overall survival in patients with various cancers and a high FCN3 expression level 7,10,19,31." (PMID 37484802, 2023). "FCN3, a circulating pattern recognition molecule of the lectin pathway, plays a role in host immune responses to cancer." (PMID 35205837, 2022). "analysis of the tumor mutation burden (TMB) and microsatellite instability (MSI) of FCNs with pan-cancer showed that FCN3 was significantly correlated with both." (PMID 35928441, 2022). "First, the expression of FCN3 was strongly down-regulated in cancer tissues compared to matched normal lung tissues, and down-regulation of FCN3 was shown to be significantly correlated with increased mortality among LUAD patients." (PMID 33859174, 2021). "Clearly, studies using cancer cells derived from these cancer types would be necessary to conclude if FCN3 functions as tumor suppressor and if a common mechanism involving the induction of ER stress is at work." (PMID 33859174, 2021). "Deimination of ficolin-3 has been previously identified only in the naked mole rat, a cancer- and hypoxia-resistant animal with unusual immunity and longevity." (PMID 32411128, 2020). "Furthermore, prior studies have confirmed that secreted or exogenous FCN3 exerts limited effects on cancer cell phenotypes, while FCN3 primarily promotes HCC cell death through its intracellular functions." (PMID 41493695, 2026). "The disparity between the outcomes from recombinant protein treatment and the stable transgenic cell lines suggests that FCN3 may exert its anti-cancer effects via its intracellular function." (PMID 38698462, 2024). "The results showed that the expression level of FCN3 was downregulated in various cancers." (PMID 36632465, 2023). "Furthermore, the ovarian expression (at both mRNA and protein level) of FCN2 and FCN3 (ficolin-2 and ficolin-3, respectively) were lower in tissue sections from malignant tumours compared with benign tumours or normal ovaries." (PMID 35326694, 2022). "Therefore, the IgM-Ficolin-3 -mediated complement activation pathway might be a new defensive strategy for human cancer immunosurveillance." (PMID 29386009, 2018). "In addition, Ficolin-3 was found to bind to IgMs, and the IgM-Ficolin-3 complex deposited on cancer cells could induce complement attack." (PMID 29386009, 2018). "We further investigated how SCNA influences gene expression and found the expression of FCN3, FREM1, MNS1, and SMOC2 was significantly positively associated with SCNA in most cancers, which indicated that aberrant SCNA of a gene might contribute to the progression of various cancers." (PMID 40297163, 2025). "We also observed a decrease in FCN3 expression in both human HCC specimens and cancer cells, accompanied by a negative regulation of MUFA abundance by FCN3 in HCC." (PMID 38698462, 2024). "However, FCN3, SLC22A1, ADH4, CYP2C8, SLC10A1, F9, and FBP1 were significantly downregulated in HCC tissue compared to the matched para-carcinoma tissue." (PMID 38664521, 2024).
cancer (continued). "In contrast, others have found the average serum concentration of ficolin-3 (not only in healthy individuals but also in cancer patients) not to exceed 40 μg/mL." (PMID 35326694, 2022). "They further reported that FCN3 preferentially binds to ovarian tissue sections of patients with malignant tumors in comparison to tissue sections of patients without." (PMID 33859174, 2021). "However, the influence of FCN3 on the overall prognosis and cancer biology of HCC are not well characterized." (PMID 36632465, 2023). "Moreover, proteomic analysis of plasma samples revealed lower levels of ficolin-3 in HCV-positive patients suffering from cancer than in those diagnosed with liver cirrhosis who did not develop HCC." (PMID 35326694, 2022). "Thus, these preparations may enable investigation of a range of ficolin-3 properties, including specificity, interactions with self and non-self cells, anti-microbial and anti-cancer activity, impacts on complement and coagulation systems, and innate-adaptive immunity crosstalk." (PMID 27232184, 2016).